HMGA2 (high mobility group AT-hook 2)
Diseases named in the same sentence as HMGA2 in open-access papers (continued):
Sharing a sentence is not in itself a finding about the gene and the disease.
leiomyoma (continued). "HMGA2 translocations were described in 45% of tumors not containing MED12 mutations, suggesting multiple, less prevalent, genetic aberrations are responsible for the remaining 55% of non-MED12 altered leiomyomas." (PMID 31027501, 2019). "Approximately 40% of leiomyomas harbor non-random cytogenetic rearrangements, of which the most common is a translocation between chromosome bands 12q15 and 14q24 leading to overexpression of high mobility group AT-hook 2 (HMGA2)." (PMID 28592321, 2017). "Aberrations in MED12, HMGA2, FH, and SRCAP complex genes account for most leiomyomas, but ~10% of leiomyomas do not harbor defects in any of these genes." (PMID 35822448, 2023). "This motivated us to explore the expression pattern of HMGA1 in our FFPE dataset, revealing significant upregulation of HMGA1 in leiomyomas of the FH subtype, but not in leiomyomas of the MED12 and HMGA2 subtypes." (PMID 33352722, 2020). "Chromosome rearrangements of 8q11∼13 but without concomitant involvement of 12q13∼15 (where HMGA2 maps) or 6p21 (where the HMGA1 gene is situated) was reported in six uterine leiomyomas, one leiomyoma of the vagina, and one intraabdominal leiomyoma." (PMID 28591699, 2017).
gastric cancer (50 papers, 2008 to 2026). A primary or metastatic malignant neoplasm involving the stomach. "The let-7 family negatively regulates HMGA2, whose elevated expression levels are associated with tumor invasiveness and unfavorable outcomes, suggesting a potential prognostic role in gastric cancer." (PMID 38542354, 2024). "Recently, a meta-analysis in gastric cancer indicated that HMGA2 overexpression is associated with poor prognosis of cancer patients." (PMID 29416690, 2018). "Our data indicate that HMGA2 is not only significantly associated with VM formation but also influences the prognosis of patients with gastric carcinoma." (PMID 28533522, 2017). "He and Wang identified that in gastric cancer cell lines, the expression of the tumor-associated protein, high-mobility group AT-hook 2 (HMGA2), was inhibited by miRNA let27." (PMID 25013480, 2014). "For instance, exosomal miR-107 modulated the HMGA2/mTOR/P-gp axis, drastically increasing the susceptibility of resistant gastric cancer cells to cisplatin, indicating that exosomal miR-107 may be a promising target in the therapy of gastric cancer." (PMID 37569598, 2023). "Thus, we conducted a meta-analysis to evaluate the association between HMGA2 expression and prognosis of gastric cancer patients." (PMID 29245994, 2017). "HMGA2 overexpression has been found in most types of human cancers, including lung, colorectal, ovarian, and gastric cancers." (PMID 38845972, 2024). "HMGA2 protein is an independent indicator of shorter patient survival time and tumor progression in several cancers, including gastric cancer, oral squamous cell carcinoma, and bladder cancer." (PMID 38845972, 2024). "Interesting research has revealed that HMGA2 is re-expressed during oncogenesis in a number of human cancers, including gastric cancer, where high HMGA2 expression is correlated with sphere formation and lymph node metastasis." (PMID 39170516, 2024). "By sponging miR-490–3p and upregulating HMGA2 expression, circFAM73A enhances stem cell-like characteristics in gastric cancer." (PMID 39170516, 2024). "HMGA2 is an oncogene that promotes gastric cancer through a progression of S-G2/M transitions and targets CDK13." (PMID 36769170, 2023). "During the progression of gastric cancer, HMGA2 transactivates TWIST1 to regulate EMT of gastric cancer cells." (PMID 36945110, 2023). "SR-4835 is an inhibitor of CDK12/13, and can target HMGA2, thereby indicating a novel mechanism of transition of gastric cancer cells." (PMID 36769170, 2023). "For instance, lncRNA HIT000218960 promotes the proliferation and migration of gastric cancer cells by overexpressing HMGA2, and miRNA let-7 affects the progression of esophageal squamous cell carcinoma by negatively regulating HMGA2." (PMID 35400282, 2022). "In summary, we develop for the first time a CRISPR/Cas9@PDA nano-delivery system that can achieve high-efficiency delivery of CRISPR/Cas9-3NLS/sgHMGA2 and high-efficiency HMGA2 gene editing of gastric cancer." (PMID 36119467, 2022). "In this study, we develop for the first time a CRISPR/Cas9@PDA nano-delivery system that can achieve high-efficiency delivery of CRISPR/Cas9-3NLS/sgHMGA2 and high-efficiency HMGA2 gene editing of gastric cancer." (PMID 36119467, 2022). "A high motility group protein HMGA2 has been revealed to regulate metastases and epithelial-to-mesenchymal transition of chemoresistant gastric cancer by up-regulating Foxl2 expression." (PMID 35053111, 2022). "N-cadherin expression is observed to be reduced in HMGA2-knocked down cells of gastric cancer, and HMGA2 elevation would exacerbate the invasive and metastatic potential of gastric cancer with the promoting effect on EMT." (PMID 35031054, 2022). "In vitro experiments showed that CRISPR/Cas9-3NLS/sgHMGA2@PDA can achieve efficient delivery of CRISPR/Cas9-3NLS/sgHMGA2 and efficient HMGA2 gene editing in gastric cancer cells, with delivery and gene editing efficiencies as high as 95% and 82%, respectively." (PMID 36119467, 2022).
gastric cancer (continued). "In contrast, lower expression of HMGA2 was found in colorectal and gastric cancers, leukemia, and lymphoma." (PMID 33668453, 2021). "HMGA2 overexpression increases the gastric cancer spherocytes, as well as expression of the markers CD44, ALDH1, SOX2, and Oct4." (PMID 33668453, 2021). "For example, OIP5-AS1 accelerated the progression of gastric cancer by regulating HMGA2 through miR-367-3p." (PMID 33821219, 2021). "Restoration of miR-34 in gastric cancer cells suppresses growth and increased apoptosis through down-regulating expression of Bcl-2, Notch, and high-mobility group AT-hook 2 (HMGA2)." (PMID 32192494, 2020). "Cordycepin reduced the expression of the EMT factors in 72 melanoma patient samples comprising HMGA2, Twist1, and ZEB1, and the inhibition of HMGA2 sensitized gastric cancer cells to chemotherapy treatment." (PMID 29853899, 2018). "HMGA2 protein levels rise acutely in malignancies, and its overexpression correlates with poor prognosis in colon, lung, pancreas, ovary and gastric cancers." (PMID 28542306, 2017). "The results of the present study indicate that higher HMGA2 levels were significantly associated with TNM stage, lymph node status, vascular invasion, and poor OS in patients with gastric cancer." (PMID 29245994, 2017). "Six studies involving 712 gastric cancer patients were included and stratified by HMGA2 amplification magnitude." (PMID 29245994, 2017). "let-7 miRNAs which generally play a tumor-suppressive role as targeting oncogenes such as RAS and HMGA2 is known to be selectively secreted into extracellular environment via exosomes to maintain tumorigenic and metastatic propensities of gastric cancer cells." (PMID 29383112, 2017). "High mobility group protein A2 (HMGA2) is a transcription factor that plays an important role in the invasion and metastasis of gastric carcinoma (GC)." (PMID 28533522, 2017). "To identify the correlation between HMGA2 and VM in GC patients, we evaluated HMGA2 expression and VM in a cohort of 228 gastric carcinoma specimens collected from the Cancer Hospital of Tianjin Medical University." (PMID 28533522, 2017). "Across our cohort, nearly 40 of the gastric carcinoma cases demonstrated high HMGA2 protein expression." (PMID 28533522, 2017). "Furthermore, a recent study reported that HMGA2 enhances gastric cancer cell survival via the mTOR/P-gp pathway, indicating the role of HMGA2 in regulating protein synthesis." (PMID 38493165, 2024). "Finally, in gastric cancers, by targeting both Bcl2 and HMGA2, miR-34a suppresses self-renewal and differentiation." (PMID 33668453, 2021). "In gastric cancer development and progression, HMGA2 was identified as oncogenes in previous study." (PMID 31249473, 2019). "HMGA2 could promote vasculogenic mimicry and tumor aggressiveness by upregulating Twist1 in gastric carcinoma." (PMID 31249473, 2019). "In addition, HMGA2 was demonstrated to play a critical role in epithelial-to-mesenchymal transition (EMT) in various cancers such as gastric cancer, hepatocellular carcinoma and nasopharyngeal cancer, thus inducing epithelial cancer invasion and metastasis." (PMID 29997523, 2018). "VM was observed in almost 65% of gastric carcinomas with high HMGA2 expression." (PMID 28533522, 2017). "Thus, it is plausible to consider that HMGA2 promotes metastasis of gastric carcinoma via induction of VM." (PMID 28533522, 2017). "An inverse correlation between HMGA2 and let-7a was found in gastric cancer cell lines." (PMID 23554630, 2010). "Another research in gastric cancer revealed that HMGA2, FOXL2, and ITGA2 were increased in metastatic lymph nodes and distant metastases in gastric cancer, and suppressing the HMGA2-FOXL2-ITGA2 pathway could serve as a new strategy in further treatment in gastric cancer." (PMID 30428899, 2018). "HMGA2 could promote the gastric cancer cell motility and EMT via increasing CD44." (PMID 28968424, 2017).
gastric cancer (continued). "In conclusion, HMGA2 may serve as a promising prognostic biomarker in gastric cancer." (PMID 29245994, 2017). "Finally, we determined whether the HMGA2-Twist1-VE-cadherin signalling pathway was critically important for mediating VM in gastric carcinoma." (PMID 28533522, 2017). "The mechanism of miR-34-mediated suppression of self-renewal might be related to the direct modulation of downstream targets Bcl-2, Notch, and HMGA2, indicating that miR-34 may be involved in gastric cancer stem cell self-renewal/differentiation decision-making." (PMID 18803879, 2008). "The mechanism of miR-34-mediated suppression of gastric cancer cell self-renewal might be related to the direct modulation of downstream targets Bcl-2, Notch, and HMGA2, implying that miR-34 may be involved in gastric cancer stem cell self-renewal/differentiation decision-making." (PMID 18803879, 2008). "The mechanism of miR-34-mediated suppression of self-renewal appears to be related to the direct modulation of downstream targets Bcl-2, Notch, and HMGA2, indicating that miR-34 may be involved in gastric cancer stem cell self-renewal/differentiation decision-making." (PMID 18803879, 2008). "In gastric cancer stem cells, E2F1 acts as a downstream transcription factor of circFAM73A/miR-490-3p/HMGA2 axis, contributing to maintain its stemness." (PMID 40886002, 2025). "In gastric cancer, OIP5-AS1 modulates the miR-367-3p/HMGA2 axis to regulate the Wnt/β-catenin and PI3K/Akt pathways, promoting cancer progression." (PMID 39401197, 2024). "In gastric carcinoma, OIP5.AS1 regulates PI3K/AKT and Wnt/β-catenin pathways in a High Mobility Group AT-Hook 2 (HMGA2)-dependent way32." (PMID 38326441, 2024). "HMGA2 and CDK13 are coexpressed in gastric cancer, and higher expression of both these genes has been associated with poor prognosis." (PMID 36769170, 2023). "We further analyzed the genes (such as MMP9, HMGA2, and KPNB1) in the gastric cancer cohort (TCGA‐STAD), and found that DR5 was positively correlated with them and higher than DR4." (PMID 37879960, 2023). "In gastric cancer cell lines MKN45 and HGC-27, linc-ROR acted in the miR-519-d-3p/HMGA2 network to promote cisplatin resistance, whilst the same resistance was demonstrated in osteosarcoma samples via miR-153-3p/ABCB1 axis." (PMID 36827545, 2023). "HMGA2 regulates epithelial–mesenchymal transition and the acquisition of tumor stem cell properties through TWIST1 in gastric cancer." (PMID 31249473, 2019). "Human gastric cancer Kato III cells with miR-34 restoration reduced the expression of target genes Bcl-2, Notch, and HMGA2." (PMID 18803879, 2008). "In this study, we demonstrated that circ_0000267 is an oncogenic circRNA that affects the progression of gastric cancer, which participates in promotion of gastric cancer cells proliferation, migration, invasion, and EMT via modulating the miR‐503‐5p/HMGA2 axis." (PMID 31845519, 2020). "Intriguingly, independent studies have shown that HMGA2 is re-expressed during oncogenesis in a variety of human malignancies, including gastric cancer, where high expression of HMGA2 correlates with lymph node metastasis, increased TNM stage and reduced patient survival in GC patients." (PMID 33731207, 2021).
glioma (44 papers, 2010 to 2025). A benign or malignant brain and spinal cord tumor that arises from glial cells (astrocytes, oligodendrocytes, ependymal cells). "In line with our results, previous studies have shown that SNP rs6581658 in the HMGA2 gene was associated with the risk of glioma and rs8756 in the 3’ UTR of the HMGA2 gene was associated with the risk of neuroblastoma." (PMID 38802807, 2024). "Because the current histopathologic criteria for glioma diagnosis cannot accurately assess patient prognosis, we performed a prognosis‐based comprehensive analysis of HMGA2 in gliomas of grades to assess the diagnostic potential of HMGA2." (PMID 29733521, 2018). "The RKIP/miR-98 to HMGA2 axis likely identifies a subpopulation of high-risk human gliomas by revealing a cellular signaling environment that is favourable to metastatic progression." (PMID 24392454, 2013). "Taken together, these data suggest a role for LIN28A in high grade gliomas and illustrate an HMGA2-associated, pro-invasive program that can be activated in GBM by LIN28A-mediated suppression of let-7 microRNAs." (PMID 23846349, 2013). "For HMGA2, a transcriptional regulator downregulated in most GNS cell lines, low or absent protein expression has been observed in glioblastoma compared to low-grade gliomas, and HMGA2 polymorphisms have been associated with survival time in glioblastoma." (PMID 23046790, 2012). "Therefore, by using immune infiltration analysis, we found HMGA2 has an association with Th2 cells, macrophages and pDCs, in glioma." (PMID 40351420, 2025). "In addition, by performing K-M curve analysis, the expression of H19, HOTAIR, miR-148a-3p, miR-222-3p, MBP and HMGA2 had a significant association with glioma patients’ survival." (PMID 40351420, 2025). "An additional study indicated that HMGA2 is a potential IDH-independent poor prognostic biomarker for glioma patients." (PMID 40351420, 2025). "Further Cox regression analysis suggested that HMGA2 can function as an independent prognostic factor for glioma patient prognosis." (PMID 40351420, 2025). "For another, we further verified the expression of HMGA2 in different glioma cohort from GEO data sets and its distribution in tumor tissues." (PMID 40351420, 2025). "To evaluate the potential effect of HMGA2 on immune infiltration in glioma, we conducted the correlation analysis of HMGA2 with various immune cell markers in glioma." (PMID 40351420, 2025). "In vitro, studies demonstrate that HMGA2 knockdown can suppresses glioma cell migration, invasion, and proliferation." (PMID 40351420, 2025). "In glioma, a HMGA2/GCN5 protein complex promoted histone acetylation in nucleosomes at AT-rich DNA sites, to cause gene activation of matrix metalloproteinase 2 (MMP2), a mediator of invasiveness in glioma, and conferring a poor prognosis." (PMID 36835656, 2023). "Together, these data show that HMGA2 is a vital target of let-7 in glioma, especially when taken with the LIN28A data discussed in Section 3.2." (PMID 37370851, 2023). "FOXD2-AS1 acts as a sponge for miR-185-5p and promotes tumorigenesis and the progression of glioma by regulating the HMGA2/PI3K/Akt pathway." (PMID 37152037, 2023). "Raf-1 kinase inhibitor protein (RKIP) decreases invasion of glioma cells by increasing miR-98 expression, which binds HMGA2 mRNA 3′ UTR to decrease HMGA2 expression." (PMID 37370851, 2023). "FOXD2-AS1 has been reported to modulate PI3K/AKT and HMGA2 downstream signaling by sponging miR-185-5p, thereby promoting tumorigenesis and tumor progression in glioma." (PMID 36588797, 2022). "FOXD2-AS1 acted as a sponge of miR-185-5p and influenced the PI3K/Akt signaling pathway by regulating HMGA2, thereby promoting glioma progression." (PMID 32793467, 2020). "A previous study revealed that FOXD2-AS1 promoted glioma progression by regulating the miR-185-5p/HMGA2 axis and the PI3K/AKT signaling pathway." (PMID 33336050, 2020).